RPL6P27 (ribosomal protein L6 pseudogene 27)
Synonyms: RPL6_10_1582
Gene: Transcribed processed pseudogene on chromosome 18 (6,462,144 to 6,463,010, reverse strand). Ensembl gene ENSG00000235552.
Diseases named in the same sentence as RPL6P27 in open-access papers:
RPL6P27 is named in the same sentence as 2 diseases in open-access papers, as found by Europe PMC text mining. Sharing a sentence is not in itself a finding about the gene and the disease.
RPL6P27 shares sentences with these, for which no sentence is quoted: Airway obstruction (1 paper); emphysema (1).